MANEA (mannosidase endo-alpha)
Synonyms: hEndo; FLJ12838; mandaselin; ENDO
Tractability: Small molecule: a structure with a bound ligand is known. Antibody: UniProt predicts a signal peptide or a membrane-spanning region. PROTAC: ubiquitination databases record sites on it; its protein half-life has been measured.
Gene: Protein-coding gene on chromosome 6 (95,577,485 to 95,609,484, forward strand). Ensembl gene ENSG00000172469.
Subcellular location: Golgi apparatus membrane
Subcellular location (Human Protein Atlas): Golgi apparatus
Pathways (Reactome):
Metabolism of proteins: N-glycan trimming and elongation in the cis-Golgi
Gene Ontology:
Molecular function: glycoprotein endo-alpha-1,2-mannosidase activity; alpha-mannosidase activity; hydrolase activity, acting on glycosyl bonds
Cellular component: Golgi apparatus; Golgi membrane
Genetic constraint (gnomAD): Loss-of-function variants: 18 observed, 28.75 expected, observed/expected ratio (o/e) 0.63, 90% interval 0.43 to 0.93. The upper end of that interval is the gene's LOEUF score, 0.93, which puts it in group 3 of 6, group 1 being the genes least tolerant of losing a copy. Missense variants: 466 observed, 494.76 expected, observed/expected ratio (o/e) 0.94, 90% interval 0.87 to 1.02. Synonymous variants: 170 observed, 169.74 expected, observed/expected ratio (o/e) 1, 90% interval 0.88 to 1.14.
Homologues: Orthologues: chimpanzee MANEA (99% identical), macaque MANEA (98% identical), guinea pig MANEA (88% identical), pig MANEA (86% identical), mouse Manea (85% identical), rat Manea (85% identical), dog MANEA (85% identical), tropical clawed frog manea (65% identical), zebrafish manea (55% identical), Drosophila melanogaster CG14015 (25% identical). Paralogues in human: MANEAL (57% identical).
Diseases named in the same sentence as MANEA in open-access papers:
MANEA is named in the same sentence as 10 diseases in open-access papers, as found by Europe PMC text mining. Sharing a sentence is not in itself a finding about the gene and the disease. The quoted sentences say what the papers report.
prostate carcinoma (2 papers, 2014 to 2018). A carcinoma that arises from epithelial cells of the prostate gland. "We then selected six genes (HNRNPH1, DSC2, FBXO9, MANEA, OR51E1, PRR15L) for validation by qRT-PCR that were over-expressed in prostate cancer across all datasets and showed high fold changes in our microarray." (PMID 25003216, 2014).
anxiety disorder (1 paper, 2021). A category of psychiatric disorders which are characterized by anxious feelings or fear often accompanied by physical symptoms associated with anxiety. "Another gene with a high likelihood of contributing to dual diagnosis phenotypes is the α-endommanosidase gene MANEA which, despite its unclarified biological function, has variants found to increase anxiety disorder risk in samples recruited from genetic studies of alcohol and drug dependence." (PMID 34201295, 2021).
oncocytoma (1 paper, 2024). "In a study aimed at distinguishing ChRCC from RO, the genes LMBRD1, TPBG, MANEA, and HACE1 were integral components of a 30-gene signature known as chromophobe and oncocytoma-related gene signature (COGS)." (PMID 39684226, 2024).
cancer (2 papers, 2009 to 2023). A tumor composed of atypical neoplastic, often pleomorphic cells that invade other tissues. "MANEA is the sole endo-acting glucoside hydrolase related to N-glycan trimming and disrupting N-linked glycosylation as therapeutic agents for cancer." (PMID 37008945, 2023). "Other candidates included DDC, MANEA, ZWINT, while ERG and SERPINA3 were examples of genes scored with decreased expression in LNCaP compared to CD26+ cancer." (PMID 20021671, 2009).
MANEA also shares sentences with these, for which no sentence is quoted: depression (1 paper); drug dependence (1); infection (1); influenza (1); ovarian carcinoma (1); tumor (1).